IL5 (interleukin 5)
Diseases named in the same sentence as IL5 in open-access papers (continued):
Sharing a sentence is not in itself a finding about the gene and the disease.
infection (continued). "As expected, a classical Th2 cytokine profile with up-regulation of IL-5, IL-13 and to a lesser extent of IL-4, but with no changes in IFNγ transcript levels, was observed in these pooled samples with expression levels peaking after the third immunising infection and immediately after challenge." (PMID 20950493, 2010). "A significant difference in the IL-5 level was found between the groups of stunted children with and without STH infection (p = 0.006)." (PMID 38393122, 2024). "Restimulation of mesenteric lymph node (mLN) cells 21 days post-infection (p.i.)with anti-CD3/CD28 induces the production of type-2 cytokines, such as IL-4, IL-5, and IL-13, in cells derived from WT mice but not in A20myel-KO mLN cells." (PMID 38680500, 2024). "Activated ILC2s produce copious amounts of type-2 cytokines (e.g. interleukin-5 (IL-5) and IL-13) which respond to non-specific alarmins such as IL-25, IL-33, and thymic stromal lymphopoietin (TSLP) under infection or insults." (PMID 37833706, 2023). "In the MLN, infection induced a clear Th2 response, shown by increased expression of the Th2 master transcription factor GATA3 and the Th2 cytokines IL-5 and IL-13 in CD4+ CD44hi cells, and this response was not affected by the blockade of IL-10 signalling." (PMID 35428872, 2022). "The concentration of certain cytokines, including CCL11, IL-1β, IL-5 and CXCL2 were similar between infected and control mice throughout the course of infection (not shown)." (PMID 35812400, 2022). "In controls, IL-5, GM-CSF, IL-13 and IFN-γ were elevated in brains from control subjects with compared to those without infection." (PMID 33723589, 2021). "Three cytokines, namely interleukin-5 (IL-5), interleukin-13 (IL-13) and macrophage inflammatory protein-2 (MIP-2), were not significantly affected by the infection." (PMID 33919457, 2021). "Consistent with previous findings, LCMV-infected WT mice showed a significant increase of CCL2 on day 3 postinfection and IL-5 on day 7 postinfection, only, while TNF, IL-1β, IL-6, IFN-γ, CCL1 and CCL22 levels did not change following infection." (PMID 32310998, 2020). "Strikingly, by d7pi, IL-5+ and IL-13+ CD4+ T cell numbers did not increase in Il17a-KO mice in response to infection." (PMID 32636457, 2020). "Similar to WT mice, in the CNS of Rag1−/− mice IFN-α1, IFN-β, TNF, IL-1α, IL-1β, IL-6, and IFN-γ mRNA levels increased following i.c. infection with ZIKV, and IL-2, IL-3, IL-4, and IL-5 mRNA was not detectable (data not shown)." (PMID 31511023, 2019). "Significantly more IL‐5 was produced following PHA stimulation in the baseline group than the post‐MDA group, regardless of a child's infection status at the end of the study." (PMID 29604074, 2018). "In Hsd11b1Del/Del mice, only IL-4 and TNF-α were significantly increased in response to the infection (respectively, p = 0.0061, 0.0061), and non-significant trends were noted for IFN-γ, IL-5 and IL-6 (respectively, p = 0.103, 0.109, 0.103)." (PMID 29062028, 2017). "For unstimulated-IL5 samples at EOI, optimal cut-off was not reliable due to low number of patients without infection (5.3%)." (PMID 29051761, 2017). "None of the increases in IL-4, IL-5, IL-9, and IL-13 in response to SEA were correlated with pretreatment infection intensity." (PMID 24357629, 2014). "We previously showed that infection with T. gondii before OVA sensitization resulted in a decrease in Ag-specific IL-4 and IL-5 production by thoracic lymph node cells with no significant increase in IFN-γ secretion." (PMID 22952678, 2012). "Individuals who were untreated and those who received a single dose of PZQ had higher IL-5 levels and a trend towards higher IL-13 levels in response to schistosome antigen AWA compared to people without infection at the two-year follow up who had not been treated." (PMID 39250522, 2024).
infection (continued). "For those plasma cytokines and chemokines with no sex-specific differences over the course of infection, a majority, including IL-2, IL-10, IFN-γ, MIP-1α, IL-3, IL-4, IL-5, IL-12p70, IL-13, IL-17, and G-CSF, exhibited differing temporal patterns between genotypes." (PMID 35970557, 2022). "However, a contradictory study showed that lack of IFN-γ led to protection from lethal infection with pandemic H1N1 and that this was dependent on ILC2 production of IL-5 and AREG which led to increased tissue integrity and reduced immunopathology." (PMID 33953732, 2021). "Recent evidence has shown that in IAV infection, there can be ample production of lung IL-5 especially in the absence of IFN-γ, which stimulates the progressive recruitment of eosinophils, particularly in the later stage of infection, i.e., during the viral clearance and host recovery phase." (PMID 34960631, 2021). "In addition, the relative level of several cytokines such as IL-5, IL-10, IL-7, IL-13 and Basic-FGF was not as impacted by the infection as the other chemokines/cytokines." (PMID 31391513, 2019). "The levels of IFN-γ, IL-4, IL-5, IL-6 and TNF-α were measured in the plasma of HP and non-HP PbNK65 1556Cl1-infected Hsd11b1Del/Del and WT mice at 21 to 24 days (HP) or 28 days (non-HP) after infection." (PMID 29062028, 2017). "However, infection of mice with mouse-adapted RAVV induces increased IFN-γ, IL-5, IL-12, CCL2, and CXCL9 relative to infection with non-lethal RAVV." (PMID 26426036, 2015). "Other cytokines were unchanged after infection (IL-2, IFN-γ, IL-5 and IL-13; data not shown)." (PMID 22024399, 2011).
tumor (342 papers, 2007 to 2026). "IL-5 production is closely correlated with the tumor, and its removal causes the serum IL-5 levels to return to normal." (PMID 41179937, 2025). "The release of these secretory products through degranulation causes tumor cell death and this process can be enhanced by several soluble mediators, including IL-5, IL-33, CCL11 and IFN-γ." (PMID 40050933, 2025). "Among Th2 cytokines, higher level of serum IL5 was associated with younger age (P = 0.049) and tumor location in the distal colon (P = 0.024)." (PMID 40928327, 2025). "IL-4, IL-5, and IL-13 are associated with the Th2 immune response, which can create an immunosuppressive environment that promotes tumor progression." (PMID 39456897, 2024). "In immunocompetent, interleukin 5-deficient (Il5–/–) mice with intrapleurally injected tumor cells, MPE formation significantly decreased." (PMID 38951159, 2024). "Some studies have confirmed that Th2 cells expressing IL-13, IL-5, and IL-4 recruit M2-like tumor-associated macrophages and contribute to tumor angiogenesis by activating STAT-646–49." (PMID 37248248, 2023). "Previous research has indicated that tumour-associated leukocytes from patients with metastatic lymph nodes secreted higher levels of IL-3 and IL-5." (PMID 36980567, 2023). "In this model, genetic deficiency or antibody-mediated neutralisation of IL-5 reduced metastasis, while adoptive transfer of eosinophils enhanced tumour spread, consistent with a pro-tumoural role." (PMID 37455828, 2023). "We showed an association between the reduction of tumor size and enhanced eosinophils influx into gastrointestinal tumors in association with IL-5 after Th2 cells administration." (PMID 36376448, 2023). "With regard to PC, Th2 cells release IL-5 and IL-13 to elevate extracellular matrix deposition and affect the development of M2 macrophages to promote fibrosis of tumor tissue which is the main causes of drug delivery difficulties as well as immunosuppression." (PMID 37371833, 2023). "IL1β, IL-2, IL-12, TNF-α, and IFN-γ, known as Th1 cytokines, are associated with good prognosis in many malignancies, whereas Th2 cytokines (IL-4, IL-5, and IL-10) are associated with tumor growth and metastasis." (PMID 36090972, 2022). "Although an oversimplification, for charting purposes, the cytokines were split into three groups by their generalized tumor-destroying (IFN-γ, IL-2, and IL-5), tumor-promoting (IL-10 and IL-4), or SIRS-associated (IL-1β, IL-6, CXCL-1, and TNF-α) properties." (PMID 35465347, 2022). "Th2 cells can secrete multiple cytokines, such as IL-4, IL-5, IL-10, and IL-13, which are associated with inflammation and tumor-promoting functions." (PMID 36193495, 2022). "Since tumor-associated myeloid cells can inhibit immune cell functions, the observed decrease in Il-4 and Il-5 together with a tendency of Il-10 in TR2myKO mice suggests a possible reduced polarization of T cells." (PMID 34868988, 2021). "Tumor-associated macrophages (TAMs) expressing M2 (alternatively activated)-like phenotype imitate type II T-helper cells that express interleukin (IL)-4, IL-5, IL-6, IL-13, and IL-10 to suppress anti-tumor immune response." (PMID 34831357, 2021). "IL-5 is critical for the development, recruitment, activation and survival of eosinophils which have been associated with anti-tumour responses and favourable CRC outcomes." (PMID 33535624, 2021). "The involvement of type 2 immunity in antitumor immune responses is reflected by studies showing that IFN-γ-deficient and, importantly, also mice deficient for the Th2 cytokines IL-4 and IL-5 show reduced tumor clearance." (PMID 34135885, 2021). "Conversely, tumor growth was markedly increased in Ccl11–/– mice, Il5–/–;Ccl11–/– and eosinophil-deficient mice." (PMID 33233582, 2020). "With respect to T cell-associated cytokines, TH2 cytokines (like IL-4, IL-5 and IL-13) were selectively elevated in tumor patients suggesting an immunosuppressed status in these patients." (PMID 30740106, 2019).
tumor (continued). "Lastly, we found dysregulated amounts of IL-4 and IL-5 cytokines, and a concomitant increase in the number of tumor associated-macrophages (TAMs)." (PMID 31555258, 2019). "The presence of a Transwell membrane between cells significantly abrogated tumor apoptosis caused by IL-33 EO, whereas it was irrelevant for IL-5 EO, implying that cell contact was absolutely required for IL-33 induced tumoricidal functions of eosinophils." (PMID 31717819, 2019). "While paraneoplastic eosinophilia is often linked with the overexpression of interleukin (IL)-5 in tumor cells, this type of diagnosis is impractical for such a rapidly evolving and life-threatening complication." (PMID 23420572, 2013). "In contrast, IFN-γ, TNF-α, IL-5, IL-4, IL-2 and low amounts of IL-10 were produced upon stimulation with the tumor cell lines encoding the HPV16E7wt and HPV16E7V constructs." (PMID 21892941, 2011). "In the experimental studies of oral carcinoma, the depletion of TATE with anti-IL-5 mAb was associated with a delayed development of the tumours." (PMID 20049171, 2009). "Moreover, Th2 cells cause IL-5 hypersecretion, which connects Th2 cells and eosinophils in their anti-tumor function." (PMID 38231074, 2025). "Research indicates that increased eosinophil infiltration within CRC tumors, potentially influenced by IL-5 and IL-3, may be linked to a better prognosis, suggesting a possible anti-tumor effect of these cells." (PMID 40500799, 2025). "Through our integrated clinical-biomarker–immunologic analyses derived from a diverse, pan-tumor cohort, we found that early increases in Th17 (IL-6, IL-17f), type 2 (IL-5, IL-13, IL-25), and type 1 (TNF-α) cytokines were associated with the development of grade ≥ 2 irAEs." (PMID 39403935, 2024). "Furthermore, tumor‐infiltrating eosinophils decrease in IL‐5‐deficient mice leading to a loss of antitumor response." (PMID 37829505, 2023). "CCT3-mediated Th2 deviation in tumor microenvironment may link to a worse outcome for LUAD, since Th2 cytokines IL-4 IL-5, IL-9 and IL-13 trigger the differentiation of tumor-associated M2 macrophages." (PMID 36918801, 2023). "Furthermore, IL-5-deficicent mice showed impaired numbers of eosinophils in the tumor and a consecutive loss of anti-tumor immunity." (PMID 34135885, 2021). "To determine whether transcripts of Th2/Treg-associated cytokines were detected in tumor lesions, we examined mRNA levels of Il4, Il5, and I10 in tongue tissues from 4NQO-treated mice." (PMID 33921389, 2021). "In the tumor tissues, we detected the association between IL-5 and Prevotella spp." (PMID 33488574, 2020). "Interestingly, Treg cell ablation resulted in increased inflammatory cytokines IL-4 and IL-5 with a concomitant reduction in classically activated tumor associated macrophages." (PMID 31555258, 2019). "Our data showed that IL-5 stimulated angiogenic responses via eNOS expression, suggesting that inflammatory cytokine may be a critical risk factor for tumor-associated angiogenesis." (PMID 28317868, 2017). "Studies have indicated that IL-5 may facilitate lung metastasis, and high expression of IL-5 in the tumor was also negatively associated with survival." (PMID 26500775, 2015). "In addition, an increase in the concentration of KC (CXCL1), a chemokine most potently expressed by tumor-associated macrophages, and IL-5, which stimulates cell migration by activating the ERK1/2 pathway, is a characteristic feature of malignant growth and metastasis." (PMID 38891915, 2024). "Inonotus hispidus spore powder (IHS) influenced T cells in ApcMin/+ mice by regulating the IL-5, -6, and -10 levels, thus suppressing tumor development." (PMID 41495793, 2026). "We also found significantly increased levels of intratumoral cytokines IFN-γ, TNF-α, and IL-5, known to be T helper 1 (Th1) and T helper 2 (Th2)-related cytokines that play a role in anti-tumor immune responses." (PMID 39743545, 2025).
tumor (continued). "These ILC2s produce granulocyte-macrophage colony-stimulating factor (GM-CSF) and interleukin-5 (IL-5), promoting the recruitment and activation of eosinophils, which have cytotoxic and tumor-suppressive functions." (PMID 40963622, 2025). "The analysis revealed that cytokines, including IFN-γ, IL-1ra, IL-8, M-CSF, MCP-1, MIP-1α, and SCGF-β, were associated with tumor height, while β-NGF, GRO-α, IL-5, IL-9, MIP-1β, TNF-β, and VEGF were linked to tumor diameter." (PMID 41048959, 2025). "A key mediator of this effect was IL-5: its increase following Th2 therapy correlated with tumor inhibition and eosinophil infiltration, although recombinant IL-5 alone induced a milder response compared to full Th2-cell administration." (PMID 40725022, 2025). "Interleukin-5 (IL-5) was the only cytokine linked to subretinal fluid, and multiple cytokines, such as M-CSF and MIF, were correlated with the tumor cell type." (PMID 41048959, 2025). "Further, tumor lysate cytokines from the combination treatment yielded elevated levels of IL-5 and G-CSF." (PMID 40568104, 2025). "ILC2s release GM-CSF, attracting eosinophils and potentially exerting anti-tumor effects by promoting their activation and recruitment through IL-5, thereby highlighting their influence within the TME." (PMID 40497988, 2025). "Intracellular IL-5 was overexpressed in the excised original tumor, as determined by immunohistochemistry." (PMID 41179937, 2025). "In particular, GM-CSF, IL-4 and IL-5, which are produced by tumor-infiltrating ILC2s, are crucial for the recruitment and cytotoxicity of eosinophils in tumor models." (PMID 39962262, 2025). "Th2 cells can activate M2 macrophages and secrete inflammatory factors such as IL-4 and IL-5, which promote tumor progression." (PMID 41471272, 2025). "Granulocyte-macrophage colony stimulating factor receptor-β (GM-CSFR-βc) is a shared component of receptors for the cytokines GM-CSF, IL-3, and IL-5, ligands with immunomodulatory and tumor promoting roles." (PMID 40075752, 2025). "Under other conditions, IL-5 from Th2 cells activates eosinophils and macrophages, yielding anti-tumor activity and growth inhibition." (PMID 41228276, 2025). "IL-5, secreted by T cells, plays a regulatory role in the production, activation, aggregation, and recruitment of eosinophils within the tumor microenvironment." (PMID 40136462, 2025). "Mechanistically, TSLP derived from cervical cancer cells up-regulated the levels of anti-inflammatory cytokines (IL-10, IL-4, IL-5 and IL-13) in eosinophils, which in turn promoted the proliferation and restricted the apoptosis of tumor cells." (PMID 40050933, 2025). "IL-33 and IL-25 activation induced ILC2s to secrete IL-5, which recruited eosinophils, thereby promoting prolonged anti-tumor immune activity." (PMID 40497988, 2025). "ILC2s secrete type 2 cytokines, including IL-5, IL-13, IL-9, and amphiregulin, which can promote tumor growth." (PMID 40497988, 2025). "Eosinophil depletion further supports an immunosuppressive phenotype, as eosinophils contribute to anti-tumor immunity via cytokine release (e.g., IL-4, IL-5) and direct cytotoxicity." (PMID 41301691, 2025). "SATB1, a global chromatin organizer, is dysregulated in human cutaneous TCL by promoting the expression of TH-2 cytokines (IL-5 and IL-9), which were appropriate for the tumor microenvironment." (PMID 39176397, 2024). "IL-5 is responsible for regulating inflammation and immune suppression in the tumor microenvironment." (PMID 38946402, 2024). "IL-4, IL-5, and IL-13, which are related to the Th2 immune response, can create an immunosuppressive environment that favors tumor growth." (PMID 39456897, 2024). "While tumor immunity is mainly governed by Th1-mediated cellular responses, we observed that preexisting higher levels of IL-5, IL-4, and IL-10 were also correlated with better clinical responses." (PMID 38231411, 2024).